IL22 (interleukin 22)
Diseases named in the same sentence as IL22 in open-access papers (continued):
Sharing a sentence is not in itself a finding about the gene and the disease.
diabetes (continued). "We performed the association study between IL-22/IL-17 cytokine expressions and some characteristics of patients (CFH, C2/CFB, C3 genotypes, age, gender, co-morbidities of diabetes, hypertension and hypercholesterolemia)." (PMID 21762495, 2011). "Importantly, IL-22 treatment downregulated expression of key genes involved in disease pathways including endocrine pancreatic dysfunction, Diabetes mellitus, severe pancreatic disorders, and impaired glucose tolerance." (PMID 38811550, 2024). "Role of IL-22 in type 2 diabetes mellitus (T2DM) during Mycobacterium tuberculosis infection." (PMID 31809521, 2019). "Since liver played a central role in metabolic hemostasis with numerous functions, we subsequently evaluated whether liver injury induced by diabetes was alleviated after IL-22 gene transfer." (PMID 28726774, 2017). "In addition, IL-22 gene transfer led to significant reduction of diabetes-induced increase of kidney index." (PMID 28726774, 2017). "The prospective association between serum IL-22 and incident type 2 diabetes was assessed in 504 initially non-diabetic study participants in both the KORA F4 study and its 7-year follow-up examination KORA FF4, 76 of whom developed diabetes." (PMID 28143481, 2017). "We investigated whether, using this dosing regimen, prophylactic IL-22 therapy would prevent diabetes, and whether therapeutic IL-22 administration would improve beta cell function or gut integrity in the NOD mouse." (PMID 28779211, 2017). "Recently, two studies indicated that IL-22 could restore mucosal immunity in diabetes by alleviating oxidative and ER stress in β-cells, which restored metabolic homeostasis." (PMID 26784895, 2016). "In addition to the production at the site of inflammation, increasing evidence indicates that IL-22 improves insulin sensitivity and lipid metabolism in diabetes and protects β cells from oxidative and ER stress, resulting in improved glycemic control." (PMID 26784895, 2016). "Additionally, IL-22 treatment improves keratinocyte prohealing functions in diabetes patients, suggesting a therapeutic potential for IL-22 in diabetic ulcer management." (PMID 27829708, 2016). "As these observations supported the hypothesis that IL-22 may exert protective functions in toxic β-cell injury, application of IL-22 was investigated in murine multiple-low-dose streptozotocin (STZ)-induced diabetes." (PMID 26793108, 2015). "Correlation between IL-22 and age, gender, BMI, duration of diabetes and HbA1c levels in T2DM." (PMID 22312190, 2012). "Correlation analysis showed that IL-22 concentrations in serum (r=0.479, p=0.009), unstimulated (r=0.672, p<0.001) and stimulated PBMCs (r=0.680, p<0.001) were positively correlated with the duration of diabetes." (PMID 22312190, 2012). "However, serum IL-22 was neither independently associated with glucose tolerance and diabetes status in a cross-sectional setting nor with risk of incident type 2 diabetes during a follow-up time of 7 years." (PMID 28143481, 2017). "In the population-based KORA F4 cohort, serum IL-22 was independently associated with male sex, current smoking, lower HDL cholesterol, lower eGFR and higher IL-1RA levels, which all represent risk factors of type 2 diabetes and/or diabetes-related complications." (PMID 28143481, 2017). "Importantly, the associations between IL-22 and cardiometabolic risk factors did not translate into an increased diabetes risk in the longitudinal part of our study." (PMID 28143481, 2017). "Diabetes induced the upregulation of serum TNF-α, IL-6, and IL-1β, and treatment with anti-ANGPTL3/IL22 showed prominent reversal compared with mIL22Fc or anti-ANGPTL3 alone." (PMID 36544775, 2022). "In contrast, higher levels of IL-22-producing Th cells were observed in humans with type 2 diabetes mellitus (DM2) and blood IL-22 levels in obese individuals were found to be elevated in DM2 patients compared to control subjects." (PMID 31817755, 2019).
diabetes (continued). "Similar to Reg2, IL-22 gene expression gradually increased with pre-diabetic age and was also increased following CFA treatment in both pre-diabetes and following the onset of diabetes." (PMID 25408874, 2013). "Our study shows that CAD classification, angiographic success, and the presence of diabetes mellitus (DM) did not influence serum IL-22 levels." (PMID 39274184, 2024). "Six-week-old NOD mice were administered bi-weekly either recombinant mouse IL-22 (200 ng/g) or PBS (vehicle control) intraperitoneally until overt diabetes was diagnosed as two consecutive measurements of non-fasting blood glucose ≥ 11 mmol/l." (PMID 28779211, 2017). "Despite these thoughtful consideration, we observed that IL-22 treatment did neither affect incidence nor course of multiple-low-dose STZ-induced diabetes." (PMID 26793108, 2015). "In summary, though biologically active on islet cells in culture, recombinant IL-22 failed to modulate disease initiation in multiple-low-dose STZ-induced diabetes." (PMID 26793108, 2015). "Additionally, the IL-22 serum and PBMC levels were positively correlated with the duration of diabetes." (PMID 22312190, 2012). "However, the CAD classification, angiography success, and presence of diabetes mellitus (DM) did not influence the serum IL-22 levels." (PMID 39274184, 2024). "IL-22 therapy did not delay the onset of diabetes in comparison with the vehicle-treated mice." (PMID 28779211, 2017). "Altogether, data indicated that administration of recombinant IL-22 may be able to ameliorate via STAT3 β-cell stress/toxicity and consequently subsequent development of diabetes, a scenario to be investigated in the well-defined model of multiple-low-dose STZ application." (PMID 26793108, 2015). "Notably, none of the two IL-22-treatment strategies affected diabetes incidence or blood glucose levels in STZ-treated mice." (PMID 26793108, 2015). "Neither IL-22 treatment protocol-1 (AB) nor protocol-2 (CD) changed onset, course, or incidence of STZ-induced diabetes." (PMID 26793108, 2015). "Taken together, despite being active on rat RINm5F insulinoma cells and murine pancreatic islets, recombinant IL-22 fails to protect pancreatic β-cells in the tested protocols from toxic effects of STZ and thus is unable to ameliorate disease in the widely used model of STZ-induced diabetes." (PMID 26793108, 2015).
metabolic syndrome (28 papers, 2015 to 2026). A cluster of metabolic risk factors for CARDIOVASCULAR DISEASES and TYPE 2 DIABETES MELLITUS. "In mice, intravenous administration of interleukin-22 (IL-22) ameliorates various disease phenotypes associated with diet-induced metabolic syndrome." (PMID 32581074, 2020). "Thus, the aim of this study was to examine the independent association of fibre intake and circulating IL-22 in participants enrolled in the Exercise in the prevention of Metabolic Syndrome (EX-MET) study." (PMID 30978932, 2019). "We investigated whether fibre intake was associated with circulating levels of IL-22 in 48 participants with metabolic syndrome (MetS)." (PMID 30978932, 2019). "ILC3-derived IL-22 are beneficial in metabolic syndrome but can also contribute to metabolic disease." (PMID 38536726, 2024). "There are some discrepancies in the literature about the impact of metabolic syndromes on IL-22 secretion." (PMID 37892881, 2023). "Insulin restores gut health and microbiota loads as well as IL-22 production, prevents microbiota encroachment, and protects against HFD-induced low-grade inflammation (LGI) and metabolic syndrome in an IL-22-dependent microbiota manner." (PMID 34944732, 2021). "Mice lacking the IL-22 receptor on a high fat diet are prone to develop metabolic syndrome and administration of IL-22 in obese mouse models reversed several symptoms such as hyperglycemia and insulin resistance." (PMID 33178196, 2020). "An animal experiment showed that fermentable fiber (inulin) significantly protected mice against high-fat-diet (HFD)-induced metabolic syndrome by nourishing microbiota to restore interleukin–22 (IL-22), and thereby mediated enterocyte function." (PMID 33138145, 2020). "On the other hand, T cell derived IL-22 amplified IL-1β driving inflammation in human adipose tissue, suggesting either a tissue specific activity of IL-22 or a disturbed action in metabolic syndrome." (PMID 33178196, 2020). "Systemic treatment with IL-22-Fc was also able to alleviate many of the metabolic syndrome defects, including lowering serum glucose, in db/db mice." (PMID 28125663, 2017). "In one example, IL-22 KO mice was utilized to verify the involvement of IL-22 expression in the process of dissecting the mechanism of fiber-mediated nourishment microbiota in gut affecting metabolic syndrome." (PMID 38605718, 2024). "However, AhR antagonists also lower IL-22; therefore, studies of partial agonists/antagonists at this receptor are needed as these agents have the ability to selectively target AhR, avoiding adverse effects such as metabolic syndrome or IL-22 downregulation." (PMID 40729204, 2023). "It is therefore possible that the enhanced wound healing by IL-22-Fc could be an indirect effect via amelioration of the metabolic syndromes." (PMID 28125663, 2017). "Furthermore, IL-22 effectively improved metabolic syndrome in diabetic mice as indicated by serum levels of triglyceride and total cholesterol that were comparable to those of normal mice." (PMID 28726774, 2017). "Conclusively, in a model of diet-induced metabolic syndrome, wild-type L. reuteri inhibited weight gain and body fat accumulation and reduced liver fat and liver triglycerides; liver fat and triglycerides were further reduced following the delivery of L. reuteri expressing IL-22." (PMID 32581074, 2020). "Because IL-22R1 can combine not only with IL-10R2 to act as a functional IL-22R complex but can also interact with IL-20R2 to form a receptor for IL-20 and IL-24, it is likely that IL-22R1 ligands other than IL-22 may play a role in ameliorating HFD-induced metabolic syndrome." (PMID 26064446, 2015). "Mechanistically, IL-22 protects against HFD-mediated inflammatory challenges and metabolic syndrome by promoting epithelium metabolism and proliferation, thus shielding protection against the gut microbiota." (PMID 34944732, 2021).
metabolic syndrome (continued). "However, it has been suggested that the benefits of inulin on low-grade inflammation and metabolic syndrome are mediated by interleukin-22, but not SCFAs." (PMID 36553814, 2022). "Rifaximin treatment reduced serum levels of several proinflammatory interleukins (IL) such as IL22 and CCL20 in both groups of patients, while IL17 and CXCL13 were only reduced in patients without metabolic syndrome manifestations." (PMID 35165326, 2022). "In contrast, several mucosal/antiviral cytokines (e.g., IL-17 and IL-22) depend more directly on CD4+ T cell abundance and are relatively uncoupled from the metabolic status, indicating that dysglycemia and dyslipidemia do not uniformly affect all immune pathways." (PMID 41601726, 2026).
tuberculosis (28 papers, 2010 to 2025). A chronic, recurrent infection caused by the bacterium Mycobacterium tuberculosis. "The elevated levels of IL-22 suggest an association between this cytokine and immunopathology during tuberculosis-IRIS." (PMID 23303806, 2013). "Since the peripheral level of MMP-9 is associated with the severity of tuberculosis, IL-22 might also regulate MMP-9 expression to control MTB infection." (PMID 36839448, 2023). "The higher levels of IL-10 may represent compensatory antiinflammatory and immune-regulatory responses, whereas elevated IL-22 levels suggest an association with immunopathology in tuberculosis-IRIS." (PMID 23303806, 2013). "In human studies, CD4+ M.tb-specific IL-17- and IL-22-producing cells have been detected in individuals exposed to tuberculosis, although only IL-22 is seen in the lung." (PMID 37415827, 2023). "Recently, we described aberrant high plasma levels of specific cytokines (i.e., IL-6, IP-10, IL-10, IL-22) in tuberculosis patients." (PMID 36650358, 2023). "PstS1 is an MTB lipoprotein that promotes the secretion of IL-22 by activating CD8α-DCs in memory T cells, implying that PstS1 is promising for the design of novel tuberculosis vaccines." (PMID 36839448, 2023). "In this study, we analyzed the concentrations of selected plasma cytokines (i.e., IL-6, IP-10, IL-10, IL-22, IFNγ, GM-CSF, IL-8) and M. tuberculosis sputum burden in patients with tuberculosis (n = 76)." (PMID 35759173, 2023). "Six of seven cytokines were significantly higher in tuberculosis patients as compared to contacts and four of these (i.e., IL-6, IP-10, IL-10, and IL-22) were detectable in the majority of tuberculosis patients." (PMID 35759173, 2023). "Moreover, IL-22 has been shown to inhibit intracellular M. tuberculosis growth in macrophages, and a polymorphism in the IL-22 promoter has been linked to increased TB risk." (PMID 35777848, 2022). "As a result, we did not analyze several ILs for which levels appear to be elevated in tuberculosis, including IL-8 and IL-22." (PMID 29216864, 2017). "In previous studies analysing lavage samples in patients with tuberculosis, T helper cells were identified as the major source of IL-22 production in BAL." (PMID 27388918, 2016). "In humans with M. tuberculosis infection, recent studies have found that memory like CD4+ T cells produce IL-22 and high level of IL-22 were present in bronchoalveolar lavage fluid of tuberculosis patients compared with those from healthy donors." (PMID 27031950, 2016). "The corresponding serum samples showed significantly higher concentrations of IL-10 and IL-22 protein in tuberculosis-IRIS patients." (PMID 23303806, 2013). "Previous work on IL-22 and IL-17 in tuberculosis immunity has demonstrated elevated levels of IL-22 in the bronchoalveolar lavage fluid of pulmonary tuberculosis patients." (PMID 23303806, 2013). "In summary, our findings show elevated levels of IL-10 and IL-22 in patients with tuberculosis-IRIS." (PMID 23303806, 2013). "Significantly higher transcript levels were observed for IL-22 in tuberculosis-IRIS patients after stimulation (P = .009), whereas levels of IL-24 transcripts were higher for non-IRIS patients (P = .020)." (PMID 23303806, 2013). "It is interesting that levels of IL-22 gene expression and serum protein were, like those of IL-10, found to be significantly higher in tuberculosis-IRIS patients." (PMID 23303806, 2013). "There was an inverse correlation between the serum concentrations of IL-10 and IL-22 (Spearman r = −0.69; P = .007) in the tuberculosis-IRIS group." (PMID 23303806, 2013). "IL-22 transcript levels were higher in both stimulated and unstimulated tuberculosis-IRIS cultures (P = .004 and P = .015, respectively)." (PMID 23303806, 2013). "Taken together, T cells actively producing IL-17 or IL-22 were preferentially expanded in the lung infection site with tuberculosis lesions, whereas IL-22-producing T cells were similarly distributed in the blood and lymphoid tissues." (PMID 20195465, 2010).
tuberculosis (continued). "Another group used in vitro antigen stimulation-based assays to detect human T cells producing IL-22 protein in cross-sectional time points of tuberculosis." (PMID 20195465, 2010). "We have recently demonstrated that primary tuberculosis can induce a 220-fold up-regulation of IL-22 transcripts in macaques." (PMID 20195465, 2010). "IL-6, IP-10, IL-10, and IL-22 were detectable in the majority of tuberculosis patients (> 50%), whereas IFNγ and GM-CSF were measurable only in minor subsets of both study groups (IFNγ: 41.1% in patients, 25.0% in contacts; GM-CSF: 21.4% in patients, 2.5% in contacts)." (PMID 35759173, 2023). "Although the roles of both IL-9 and IL-22 in the pathogenesis of both tuberculosis and SARS-CoV-2 remain unclear, both were upregulated in the superinfected mice at both time points, an outcome that warrants future studies." (PMID 36200898, 2022). "In addition, IFNG and IL22 gene expression is also increased in tuberculosis LN, but the expression of IL17A was unaffected." (PMID 33057074, 2020). "Since IL-26 and IL-22 can also be secreted by other tuberculosis-associated lymphocyte subsets than TH17 such as TH1 cells or by NK cells, our findings point to TH1 cells or NK cells as cellular source of IL-26 in granulomatous lesions of tuberculosis." (PMID 33057074, 2020). "In chronic infections such as tuberculosis, IL-22 seems to play a disease promoting role." (PMID 27388918, 2016). "Similarly, significantly higher levels of IL-22 (P = .007) were detected in the serum samples of tuberculosis-IRIS patients (median, 53.2 pg/mL [IQR, 11.31–188.8 pg/mL]), compared with non-IRIS patients (median, 24.4 pg/mL [IQR, 15.7–43.8 pg/mL])." (PMID 23303806, 2013). "We show that IL-22 may be implicated not only in tuberculosis pathology, but also in tuberculosis-IRIS immunopathology, as indicated by the higher concentrations of IL-22 we observed in tuberculosis-IRIS patients." (PMID 23303806, 2013). "We hypothesized that IL-17 and IL-22 contribute to the inflammatory response in pleural and pericardial disease sites of human tuberculosis (TB)." (PMID 21767990, 2011). "In this case, potent activation of Vγ2Vδ2 T cells driven by high-level production of HMBPP in severe tuberculosis may potentially down-regulate IL-22-production and antagonize IL-22-producing T cell-mediated inflammation." (PMID 20195465, 2010). "Elucidation of these aspects may potentially device immune regulatory strategy in which immune responses of IL-22-producing T cells can be balanced to facilitate protective response but minimize inflammatory consequence in tuberculosis." (PMID 20195465, 2010). "Patients with tuberculosis (TB) show accumulation of memory-like NK cells in the pleural fluid, with this sub-population producing more IL-22 and IFN-γ when co-cultured with BCG-infected monocytes." (PMID 37520720, 2023). "In addition to these murine, nonhuman primate, and in vitro models demonstrating a role for IL-22 in M. tuberculosis control, a human genetic study described polymorphisms in the promoter region of IL-22 leading to decreased IL-22 production that were associated with greater TB susceptibility." (PMID 35777848, 2022). "However, in humans, IL-22 is directly involved in the specific response to tuberculosis." (PMID 27375607, 2016). "CD4 T cells and granulocytes produce IL-22; however, the effector CD4 T cells from TB patients only increase IL-22 production when stimulated with M. tuberculosis proteins in vitro." (PMID 27375607, 2016). "The coexpression of IL-10 and IL-22 seen in our study and their inverse correlation in tuberculosis-IRIS patients supports the suggestion that there may be interaction between these cytokines in this condition (and not in controls), as has been postulated for other diseases." (PMID 23303806, 2013).